CIP2A (cellular inhibitor of PP2A)
Diseases named in the same sentence as CIP2A in open-access papers (continued):
Sharing a sentence is not in itself a finding about the gene and the disease.
bladder cancer (6 papers, 2012 to 2023). "Also, the specific CIP2A protein expression frequency increased with increasing tumor grade and cancer stage, which suggests an association with the aggressiveness of bladder cancer." (PMID 23342256, 2012). "CIP2A might serve as a prognostic marker because our study showed that overexpression of CIP2A protein was associated with tumorigenicity of bladder cancer and with high-grade, high-stage, invasive tumors." (PMID 23342256, 2012). "Overexpression of CIP2A in PDAC, clear cell renal cell carcinoma or bladder cancer was shown to promote cellular EMT and was associated with poor prognosis." (PMID 37170215, 2023). "And both in vitro and in vivo experiments demonstrated that exogenous FN dramatically promoted cell proliferation and CIP2A expression in bladder cancer cells." (PMID 28521777, 2017). "Meanwhile, in human bladder cancer cell lines (T24 and J82), exogenous FN significantly promoted cell proliferation, however, CIP2A depletion inhibited this process." (PMID 28521777, 2017). "Recent studies have shown that CIP2A enhances cell proliferative capacity in various malignant disorders, including bladder cancer." (PMID 28521777, 2017). "Due to the short postoperative time, lack of follow-up information hinders the exploration of the linkage between prognosis and FN or CIP2A expression for bladder cancer in our study." (PMID 28521777, 2017). "In this study, we provide evidence that CIP2A is involved in FN-induced bladder cancer proliferation by enhancing β-catenin stabilization." (PMID 28521777, 2017). "The roles of FN and CIP2A in regulating bladder cancer cell proliferation were evaluated in cell and animal models." (PMID 28521777, 2017). "In sum, these results demonstrate that CIP2A increases the stability of β-catenin protein in bladder cancer cells." (PMID 28521777, 2017). "Taken together, these observations suggest that CIP2A mediates FN-induced bladder cancer cell proliferation." (PMID 28521777, 2017). "Initially, we evaluated the association of the expression levels among FN, CIP2A and PCNA in bladder cancer tissue samples (n = 68)." (PMID 28521777, 2017). "Apart from promoting cell proliferation, the roles that FN and CIP2A played in bladder cancer deserve for further research." (PMID 28521777, 2017). "Their studies supported the role of CIP2A in bladder cancer progression and indicated the usefulness of CIP2A for the surveillance of recurrence or progression of human bladder cancer." (PMID 25015035, 2014). "In summary, this preliminary study reports that CIP2A is an oncogene involved in bladder cancer as it is specifically expressed in bladder tumor tissue and not normal tissue." (PMID 23342256, 2012). "Our studies reported here support the role of CIP2A in bladder cancer progression and its usefulness for the surveillance of recurrence or progression of human bladder cancer." (PMID 23342256, 2012). "In this study, Western blot analysis was used to assess the expression level of CIP2A protein in bladder cancer cell lines and bladder cancer patient tissues (n = 43)." (PMID 23342256, 2012). "Here, we identified elevated expression of cancerous inhibitor of protein phosphatase 2A (CIP2A) in bladder cancer." (PMID 23342256, 2012). "Our study also indicated that CIP2A protein expression levels increased concomitantly with the progression of bladder cancer." (PMID 23342256, 2012). "This study determined the overall sensitivity and specificity of CIP2A protein expression in bladder cancer tissue to be 42% and 100%, respectively." (PMID 23342256, 2012). "We have identified the cancerous inhibitor of PP2A (CIP2A) protein as a novel bladder cancer biomarker." (PMID 23342256, 2012). "Similarly, our data demonstrated that MIBC tissues possessed higher levels of FN than NMIBC samples, and in addition, CIP2A promoted bladder cancer cell proliferation via abrogating G0/G1 arrest, which is similar to previous studies." (PMID 28521777, 2017).
bladder cancer (continued). "The clinical relevance of CIP2A oncoprotein in bladder cancer aggressiveness has been established." (PMID 28521777, 2017). "Although the relationship between the overexpression of CIP2A and aberrant cell proliferation in bladder cancer has been confirmed previously, the cause of CIP2A overexpression and the mechanisms though which CIP2A exerts its proliferative properties in bladder cancer are still unclear." (PMID 28521777, 2017). "Moreover, we validate that FN promotes bladder cancer cell proliferation by increasing CIP2A expression in cell and animal models." (PMID 28521777, 2017). "Promisingly, FN and CIP2A could serve as potential therapeutic targets for bladder cancer treatment." (PMID 28521777, 2017). "Here, we investigated whether FN regulates CIP2A expression to promote bladder cancer cell proliferation." (PMID 28521777, 2017). "The following western blotting assays further strengthened the evidence linking FN with CIP2A in bladder cancer tissues (n = 68), meanwhile, Spearman’s correlation analysis revealed the positive correlation between the gray value of CIP2A and PCNA (r = 0.459, P < 0.001)." (PMID 28521777, 2017). "Given that numerous proliferation-related signal pathways were activated by FN in other cancer models, we tested the effect of exogenous FN on CIP2A overexpressing bladder cancer cells to further ascertain that FN-mediated proliferation was primarily driven by increased CIP2A expression." (PMID 28521777, 2017). "Furthermore, co-IP showed that CIP2A and β-catenin were seen in the cell lysate of T24 and J82 cells, and both proteins were immunoprecipitated with CIP2A antibody from cell lysate, indicating that the CIP2A interacts with β-catenin in bladder cancer cells." (PMID 28521777, 2017). "In this study, we examined if CIP2A is expressed in bladder cancer tissues." (PMID 23342256, 2012). "Of 43 bladder cancer tissues, CIP2A was expressed in 18 of them." (PMID 23342256, 2012). "Only 12% of bladder cancer patients with pTa tumor overexpressed CIP2A protein." (PMID 23342256, 2012). "Thus, based upon a favorable outcome we further examined and report CIP2A protein detection in human bladder cancer tissues." (PMID 23342256, 2012). "Therefore, we postulated that CIP2A mediated FN-induced bladder cancer cell proliferation." (PMID 28521777, 2017). "The correlations of stromal FN with CIP2A and proliferating cell nuclear antigen (PCNA) expression were analyzed in a cohort bladder cancer patients." (PMID 28521777, 2017). "Here we demonstrate the positive correlations of stromal FN with CIP2A and PCNA expression in a cohort human bladder cancer tissues." (PMID 28521777, 2017). "In this study, we found that stromal FN expression correlated positively with the levels of CIP2A and PCNA in bladder cancer tissues." (PMID 28521777, 2017). "To further confirm the proposed role of CIP2A in FN-induced cell proliferation of bladder cancer cells, we established subcutaneous xenograft models in BALB/c nude mice by using sh-CIP2A and sh-Control T24 cells." (PMID 28521777, 2017). "In bladder cancer, we additionally found fibroblast growth factor receptor 1 (FGFR1) and its downstream regulatory subunits of the protein phosphatase 2 (PP2; inhibitor of cell growth and division), and the pro-proliferative inhibitor of PP2, KIAA1524 (CIP2A)." (PMID 28775339, 2017). "Subsequently, bladder cancer cells that overexpressed CIP2A proliferated fast, however, FN stimulation lacked the ability to enhance the proliferative capacity of CIP2A-overexpressed T24 and J82 cells significantly." (PMID 28521777, 2017). "CIP2A protein was also abundantly expressed in bladder cancer cell lines while it was not expressed in non-neoplastic epithelial cell lines." (PMID 25015035, 2014). "We also would like to emphasize that the combined sensitivity of CIP2A in noninvasive pTa and pT1 stages is only 19%, suggesting that CIP2A is not an ideal biomarker for the early detection of bladder cancer." (PMID 23342256, 2012).
bladder cancer (continued). "Our studies indicated CIP2A protein was abundantly expressed in bladder cancer cell lines but not in nontumor epithelial cell lines." (PMID 23342256, 2012). "The CIP2A expression in bladder cancer has not been reported so far." (PMID 23342256, 2012).
glioma (6 papers, 2022 to 2025). A benign or malignant brain and spinal cord tumor that arises from glial cells (astrocytes, oligodendrocytes, ependymal cells). "In glioma tissues and cells, miR-383 downregulation causes the upregulation of CIP2A, which was linked with larger tumor size, higher grade, and shorter survival time in patients." (PMID 36313570, 2022). "In gliomas, CIP2A is overexpressed and associated with tumor size, WHO grade and overall postoperative survival rate." (PMID 36555359, 2022). "In summary, CIP2A is involved in the development and progression of glioma, but its mechanisms in gliomas are still complex and unclear, so further studies are needed to define its mechanism of action." (PMID 36555359, 2022). "Overexpression of miR-383 reduced CIP2A expression in glioma cells, thereby suppressing tumor growth." (PMID 36313570, 2022). "Their study also demonstrated that CIP2A depletion inhibited glioma cell proliferation, migration and invasion." (PMID 36555359, 2022). "In glioma cells, CIP2A overexpression promoted cell proliferation and invasion." (PMID 36313570, 2022). "Therefore, depletion of CIP2A inhibits the cellular proliferation of gliomas." (PMID 36555359, 2022). "Therefore, they hypothesize that CIP2A was involved in glioma progression, indicating that CIP2A could be used as a potential therapeutic target in the future." (PMID 36555359, 2022). "Therefore, further studies are needed to understand whether CIP2A may represent a new drug target for glioma." (PMID 36555359, 2022).
renal cell carcinoma (6 papers, 2011 to 2026). "Expression of CIP2A in renal cell carcinomas correlated with tumor invasion, metastasis and patients' survival." (PMID 25015035, 2014). "The objective of this study was to detect the potential effects of CIP2A in renal cell carcinomas (RCCs)." (PMID 22075943, 2011).
breast tumor (5 papers, 2012 to 2022). "CIP2A overexpression clustered mainly with basal-like breast tumours." (PMID 24460909, 2014). "However, our observations highlight the existence of alternative mechanisms that regulate AKT signaling in a subgroup of breast tumors without altered CIP2A expression that determines its independent value as a marker of poor outcome in this disease." (PMID 35329936, 2022).
pancreatic cancer (5 papers, 2014 to 2023). "To elucidate the underlying mechanisms by which CIP2A promoted chemo-resistance of pancreatic cancer cells, we investigated the expression of several key proteins in CIP2A knockdown SW1990 and SW1990/R cells." (PMID 26894380, 2016). "The association of CIP2A expression with p-AKT level was analyzed in drug resistant pancreatic cancer cells." (PMID 26894380, 2016). "Similar results were also observed when the pancreatic cancers were divided into two groups based on their CIP2A expression levels (right)." (PMID 36463234, 2022). "The positive rate of CIP2A protein expression in pancreatic cancer tissue was70.83 %, which was significantly higher than that in adjacent non- cancerous pancreatic tissue (11.11%)." (PMID 26894380, 2016). "Western blots analysis confirmed that the protein level of CIP2A increased in pancreatic cancer cells." (PMID 26894380, 2016). "Compared to the DT cell, CIP2A mRNA expression was high in 8 out of the 9 (88%) pancreatic cancer cell lines." (PMID 26894380, 2016). "We found 51 out of 72 (70.83%) cancer cases had positive CIP2A expression in the cytoplasm of pancreatic cancer cells." (PMID 26894380, 2016). "We knocked down CIP2A in pancreatic cancer cells and investigated the drug sensitivity of cancer cells to gemcitabine treatment." (PMID 26894380, 2016). "We found that down regulating CIP2A resulted in the down regulation of p-AKT gene in both pancreatic cancer cells and drug-resistant cells." (PMID 26894380, 2016). "Recent studies have found that Cancerous inhibitor of protein phosphatase 2A (CIP2A) is expressed in pancreatic cancer, which play a role in cancer as an oncoprotein." (PMID 26894380, 2016). "The result showed that knocking down CIP2A increased sensitivity to gemcitabine in pancreatic cancer cells." (PMID 26894380, 2016). "Cancerous inhibitor of protein phosphatase 2A (CIP2A) is an oncoprotein which participates in inhibiting tumor apoptosis in pancreatic cancer cells." (PMID 26894380, 2016). "In this study, we applied immunohistochemical staining to investigate the expression of CIP2A protein in normal and pancreatic tumor tissues." (PMID 26894380, 2016). "Indeed, in human pancreatic cancers with KRAS mutations, SET/CIP2A overexpression correlates with the increased expression of IEGs, resulting in poor clinical outcomes." (PMID 36463234, 2022). "We tested CIP2A mRNA expression in 9 pancreatic cancer cell lines." (PMID 26894380, 2016). "Taken together, we show that CIP2A is over-expressed in PDAC and could be an oncoprotein, CIP2A can inhibit apoptosis of pancreatic cancer cells." (PMID 26894380, 2016). "Our results indicated that down-regulation of CIP2A could be a novel therapeutic strategy for pancreatic cancer." (PMID 26894380, 2016). "In addition, down-regulation of CIP2A inhibited cell proliferation and increased sensitivity to gemcitabine in pancreatic cancer cells by decreasing AKT signaling pathway." (PMID 26894380, 2016). "Furthermore, the effect of CIP2A in cancer cell proliferation and apoptosis was investigated in pancreatic cancer cells." (PMID 26894380, 2016). "Their results indicated that antagonizing SET and/or CIP2A may be an innovative approach for the treatment of human pancreatic cancer." (PMID 25015035, 2014). "Furthermore, scatter plot analyses showed significant positive correlations of SET/CIP2A expression with the expression levels of the IEGs (TRIB1, SPRY4, CTGF) and with those of growth-promoting genes (cyclin D1, E2, and PCNA) in KRAS-mutated pancreatic cancers." (PMID 36463234, 2022).
tongue cancer (5 papers, 2011 to 2014). A malignant neoplasm affecting the tongue. "High CIP2A immunoreactivity predicted poor survival in tongue cancer patients (P=0.027, logrank test)." (PMID 21610708, 2011). "In conclusion, in tongue cancer, high cytoplasmic CIP2A expression characterises aggressive disease and is an independent prognostic marker indicating need for adjuvant treatment after surgery." (PMID 21610708, 2011). "High CIP2A expression was able to predict poor prognosis within clinically important subgroups of tongue cancer patients, such as in pT2 tumours and in young patients." (PMID 21610708, 2011). "It is possible that CIP2A and c-Myc have different expression levels in tongue cancer than in other cancers studied before." (PMID 21610708, 2011). "High CIP2A immuno-reactivity was an independent prognostic indicator in early-stage tongue cancer." (PMID 25015035, 2014). "The possible route by which CIP2A affects the aggressiveness and poor outcome in tongue cancer may be through the Akt signalling pathway." (PMID 21610708, 2011). "In our present study we show that CIP2A is an independent prognostic factor in tongue cancer." (PMID 21610708, 2011).
glioblastoma (4 papers, 2022 to 2025). The most malignant astrocytic tumor (WHO grade IV). "Additionally, during hypoglycemia, metformin promotes glioblastoma cell apoptosis by inhibiting the Cancerous Inhibitor of Protein Phosphatase 2 A (CIP2A) and activating the PP2A B56δ subunit." (PMID 41276810, 2025). "It has been shown that in more than 50% (59.6%) of glioblastoma cases, the activity of PP2A is inactivated or dysregulated due to overexpression of its inhibitors, especially SET and CIP2A." (PMID 36555359, 2022). "CuB prevents proliferation and invasion in human glioblastoma multiforme (GBM) cell lines, in addition to downregulating the expression of the oncoprotein CIP2A and its downstream signaling molecule phospho-Akt, suggesting that CuB could be a potential inhibitor of CIP2A." (PMID 36355498, 2022).
lymph node metastasis (4 papers, 2011 to 2022). "The CIP2A immunostaining level was positively correlated with primary tumour stage, lymph node metastasis, distant metastasis, TNM stage and histological grade (all P<0.05)." (PMID 22075943, 2011). "Furthermore, the CIP2A staining level significantly correlated with primary tumour stage, lymph node metastasis, distant metastasis, TNM stage and histological grade (all P<0.05)." (PMID 22075943, 2011).
serous ovarian cancer (4 papers, 2011 to 2019). "We evaluated CIP2A expression separately for cytoplasmic and nuclear immunoreactivity in 562 serous ovarian cancer specimens, of which 524 (93%) were scored successfully." (PMID 21897396, 2011). "In conclusion, our results demonstrate that overexpression of cytoplasmic CIP2A in serous ovarian cancer serves as an indicator of poor overall and progression-free survival." (PMID 21897396, 2011). "Indeed, a retrospective analysis of serous ovarian cancer demonstrated 40.4% of the specimens to have strong CIP2A immunoreactivity and another 42.4% had weak positive staining." (PMID 31214504, 2019). "CIP2A protein expression is a novel marker of reduced survival in serous ovarian cancer patients." (PMID 25015035, 2014). "A prognostic role for CIP2A expression has been reported in serous ovarian cancer." (PMID 25015035, 2014).
testicular cancer (4 papers, 2012 to 2021). A primary or metastatic malignant neoplasm that affects the testis. "Octamer-binding transcription factor 4 (OCT4) and cancerous inhibitor of protein phosphatase 2A (CIP2A) are upregulated in testicular cancer and cell lines." (PMID 34513828, 2021). "Together these results demonstrate that CIP2A is a novel Oct4 target gene in normal and malignant stem cell-like cells, and that they are co-expressed in vivo in testicular cancers with characteristics of stem cell–like cell growth." (PMID 25474139, 2015). "In order to study the importance of Oct4 and CIP2A co-expression in other than testicular cancers, we used HNSCC cell lines and patient specimens." (PMID 25474139, 2015). "Oct4 positively regulates CIP2A expression both in testicular cancer cell lines as well as in embryonic stem cells." (PMID 25474139, 2015). "On the other hand, MYC was co-expressed with CIP2A in testicular cancers." (PMID 29527532, 2016). "Results above identify CIP2A as a novel Oct4 target gene in testicular cancer cells." (PMID 25474139, 2015). "Therefore, it will be important to elucidate in the future whether testicular CIP2A function is altered in male infertility patients or whether CIP2A contributes to development of testicular cancers." (PMID 22461891, 2012).
Cognitive impairment (3 papers, 2022 to 2024). Abnormal cognition is characterized by deficits in thinking, reasoning, or remembering. "Consistent with our previous findings in CIP2A-overexpressed mice, the Chk1 overexpression resulted in remarkable synaptic dysfunction and severe cognitive impairment in mice, which mimics the changes in AD patients." (PMID 35286657, 2022). "Accumulation of DNA damage drives activation of cell cycle checkpoint protein kinase 1 (Chk1), upregulation of cancerous inhibitor of PP2A (CIP2A), tau hyperphosphorylation, and Aβ overproduction, eventually resulting in synaptic impairment and cognitive deficits." (PMID 38819231, 2024).